CCR4 (C-C motif chemokine receptor 4)
Diseases named in the same sentence as CCR4 in open-access papers (continued):
Sharing a sentence is not in itself a finding about the gene and the disease.
breast cancer (50 papers, 2011 to 2025). A primary or metastatic malignant neoplasm involving the breast. "Recently, the CCR4 expression level in breast cancer was reported to be associated with lung metastasis." (PMID 28039457, 2017). "Clinical trials revealed the important role of CCR4 in cancers, such as leukemia/lymphoma, breast cancer, and renal cancer." (PMID 36555280, 2022). "With this in mind, we aimed to confirm the positive association between CCR4 and FOXP3 in other cohorts of breast cancer patients." (PMID 35222362, 2022). "We found that tumor-infiltrating Tregs express a higher expression of the chemokine receptor CCR4 than peripheral Tregs in breast cancer patients." (PMID 35222362, 2022). "We obtained peripheral blood and post-operative breast tumor tissue from a cohort of 8 breast cancer patients undergoing surgery to establish the expression pattern of CCR4 in Tregs." (PMID 35222362, 2022). "The FOXP3+CCR4+ Tregs from breast cancer patients’ peripheral circulation infiltrate tumor site in response to TME-secreted CCL17 and CCL22." (PMID 35222362, 2022). "CCL22 production by tumor cells was identified as a mechanism of immune escape in breast cancer, through CCR4+ Treg recruitment in the tumor microenvironment (TME), induced by IFNγ exposure." (PMID 35794623, 2022). "Previous studies have reported that overexpression of CCL2 and its receptors, CCR2, and CCR4, in human cancers, promote lung cancer, breast cancer, and HNSCC development via regulation of angiogenesis, cell proliferation, and migration." (PMID 35177591, 2022). "This does not exclude the possibility that targeting CCR4 would be more effective in several cancer diseases in which cancer cells are also CCR4+, among them breast cancer." (PMID 34944943, 2021). "Others have reported high expression of CCR4 by Tregs in the blood of breast cancer patients, with migratory capabilities to CCL22 and CCL17." (PMID 34632244, 2021). "Our findings illustrated that Notch3-regulating CCL2/CCR4 axis should be an important signaling pathway for mammary gland development and should be a candidate target for breast cancer therapy." (PMID 33244467, 2020). "At the same time, we also report that Notch3 knockdown can inhibit the proliferation and the migration of 4T1 murine mammary carcinoma cells via the CCL2/CCR4 axis." (PMID 33244467, 2020). "Reference 81 to “Li, J.Y.; Ou, Z.L.; Yu, S.J.; Gu, X.L.; Yang, C.; Chen, A.X.; Di, G.H.; Shen, Z.Z.; Shao, Z.M. The chemokine receptor CCR4 promotes tumor growth and lung metastasis in breast cancer." (PMID 31146450, 2019). "The correct reference is “Li, J.Y.; Ou, Z.L.; Yu, S.J.; Gu, X.L.; Yang, C.; Chen, A.X.; Di, G.H.; Shen, Z.Z.; Shao, Z.M. The chemokine receptor CCR4 promotes tumor growth and lung metastasis in breast cancer." (PMID 31146450, 2019). "In breast cancer, CCR4 expression positively correlates with HER2 expression, tumor recurrence, and lymph node, lung, and bone metastasis, as it enhances chemotaxis to CCL17." (PMID 30591657, 2018). "The significant differences in HCC cells proliferation by CCR4 between in vitro and in vivo studies in our research are consistent with Lee’s20 and Li’s21 findings in gastric cancer cells and breast cancer cells." (PMID 28959024, 2017). "The CCR4 (receptor of CCL17 and CCL22) expression level in breast cancer was reported to be associated with lung metastasis." (PMID 28039457, 2017). "The functionof CCR4 has been previously elucidated in both hematologic malignancies and solid tumors such as gastric cancer, breast cancer and lung cancer." (PMID 27356745, 2016). "It has been reported that CCR4 overexpresion can enhance metastatic potential in breast cancer and lung cancer." (PMID 27356745, 2016). "Interestingly, since the expression of CCR4 is higher in Tregs than other CD4+ T cells, probably because of a FOXP3 responsive element on the CCR4 promoter, Tregs infiltration is favored in some tumors, e.g., in breast cancer." (PMID 39596815, 2024).
breast cancer (continued). "Our current research focuses on CCR4 modulation in Tregs and its implications for breast cancer." (PMID 35222362, 2022). "Because CCR4 is a tumor-specific chemokine receptor, we examined its expression in Tregs from both the peripheral circulation (source) and the tumor site (destination) in breast cancer patients." (PMID 35222362, 2022). "Suppression of CCR4 could suppress the migration, invasion, and proliferation for several cancers, such as lung cancer, breast cancer, and leukemia." (PMID 35619698, 2022). "Strategies that target CCR4-positive Treg cells may have significant benefits in the control of breast cancer metastasis by protecting adaptive immune responses." (PMID 36555280, 2022). "After the occurrence of tumour metastasis, breast cancer cells could stimulate lung tissue to secrete CCL17 and CCL22, which attract CCR4-positive Treg cells to accumulate in lung tissue, and thus facilitating lung metastasis of breast cancer." (PMID 36569832, 2022). "Previously our laboratory implicated the CCR4-NOT complex as an important determinant for metastatic mammary cancer." (PMID 26807845, 2016). "However, in breast cancer patients, the expression of chemokine receptor CCR4 in tumor infiltrating Tregs is higher than that in peripheral Tregs, The expression of FOXP3 in breast cancer tissue is higher than that in normal tissue, and overexpression of FOXP3 is associated with better prognosis." (PMID 38919615, 2024). "CCL2 and CCR4 or CCR2 have been proposed as a potential target for decreasing myeloid-derived suppressor cells (MDSCs) and tumor-associated macrophages (TAMs) recruitment in prostate cancer, breast cancer, malignant glioma, colorectal cancer, and lung carcinoma." (PMID 39046599, 2024). "However, little is known regarding CCR4 transcriptional regulation in Treg cells in breast cancer." (PMID 35222362, 2022). "In breast cancer, tumour‐derived chemokines such as CCL22 and CCL1 bind to CCR4 and CCR8 on Tregs, guiding their migration into tumour tissues." (PMID 41200753, 2025). "Specifically, in breast cancer, the chemokine receptors that exhibited the most significant correlations were CCR2, CCR4, CCR5, CCR6, CCR8, CXCR2, and CX3CR1." (PMID 40649753, 2025). "The screening results showed that none of the receptors for Cx3cl1 (CX3CR1), Cxcl16 (CXCR6), Ccl17 (CCR4, DARC, CCR10) or IL6 (IL6R) was more expressed in basal B compared to basal A or luminal breast cancer cells." (PMID 38055067, 2023). "In both mammary carcinoma- and melanoma-bearing mice, ablation of FOXP3 reduces the generation of CCR4+ Tregs and hence their infiltration into the tumor site." (PMID 35222362, 2022). "The CCL17/C-C chemokine receptor 4 (CCR4) axis has been recently reported to induce the migration of hepatocellular carcinoma cells 17 and enhance epithelial-mesenchymal transition (EMT) in breast cancer via Akt signaling." (PMID 33664865, 2021). "By contrast, both Ccr4/CNOT6 and Ccr4/CNOT6L are required for proliferation of human MCF-7 breast carcinoma cells." (PMID 24391663, 2013). "Additionally, it has previously been described that HER2- ER+/− breast cancer patients had an increased frequency of Th2/ Th17 cells, based on the surface marker expression of CXCR3, CCR4, and CCR667." (PMID 39843922, 2025). "Furthermore, subsets of CD8 + T cells displayed expression of CCR2 and CCR4, albeit to a lower extent than CXCR3, in human CRC, pancreatic neuroendocrine and breast cancers." (PMID 40595293, 2025). "We wanted to see if this phenomenon was true in the in vivo animal model because both breast cancer patient-derived Tregs and ex vivo-generated Treg cells showed a dependency of FOXP3 in the transcriptional regulation of CCR4, the key regulator of Treg infiltration in the TME." (PMID 35222362, 2022).
breast cancer (continued). "Our findings illustrated that Notch3 signaling activation is necessary for the development of the mammary gland, but its hyperactivation closely relates to breast cancer progression, and that Notch3-regulating CCL2/CCR4 axis should be the target for breast cancer therapy." (PMID 33244467, 2020). "Studies from a breast cancer mouse model and human patient data demonstrate a negative correlation between CNOT2 expression and tumor development and the CCR4-NOT complex was implicated in tumor cell metastasis." (PMID 31724941, 2019). "CCR4, whose ligands are CCL2, CCL3, CCL5, CCL17 and CCL22, is crucial for immune cell homeostasis but is also involved in hematologic malignancies, such as adult T-cell leukemia and Hodgkin’s lymphomas, and some solid tumors, including breast cancer." (PMID 30591657, 2018). "Generation of co-expressed gene maps from mouse strains with differing inherited sensitivity for pulmonary metastasis identified a network module centered on the CCR4-NOT component Cnot2 that was capable of discriminating breast cancer patient outcome." (PMID 26807845, 2016). "In this study we have begun to dissect the role of CCR4-NOT in mammary tumor metastasis by investigating the role of RNA deadenylation in tumor progression." (PMID 26807845, 2016). "Recent studies on breast cancers have shown that two of these chemokines, CCL20 and CCL22, may recruit Treg that express the corresponding chemokine receptors CCR6 and CCR4." (PMID 21521526, 2011). "In breast cancer (BC), M2 macrophages produced CCL17 that induced EMT gene (N-cadherin, vimentin and PCNA) expression in tumors via CCL17/CCR4/mTORC1 axis." (PMID 38794298, 2024). "CX3CL1 and CXCL13 were shown to play an important role in the brain extravasation of breast cancer, while the following cytokines/chemokines were involved in the extravasation of melanoma cells (9IL-23, CXCL10, CXCR3, CXCL10 receptor, CCR4, CCL17, and CCR4) and lung cancer cells (TNF-α and CX3CR1)." (PMID 37190188, 2023). "Thus, it is not surprising that a strong correlation between CCR4 expression and lower overall survival and disease-free survival was reported in breast cancer patients." (PMID 30591657, 2018). "CCR4 is expressed in T-cell leukemia, non-lymphoid solid tumors, such as breast cancer, lung cancer, colorectal cancer, gastric and hepatocellular carcinoma, where it may contribute to the proliferation of tumor cells and chemotaxis of regulatory T cells." (PMID 30140381, 2018). "This include the Steroid 5-alpha-reductase SRD5A1, the CCR4-NOT component RQCD1 and the Rab11 effector protein RAB11FIP1 which have all been reported as up-regulated in breast cancers." (PMID 22691140, 2012). "In breast cancer, CCL22 has been shown to be chemoattractive for CCR4+, but not CCR4- T-reg." (PMID 37063842, 2023).
melanoma (48 papers, 2013 to 2025). A malignant, usually aggressive tumor composed of atypical, neoplastic melanocytes. "Functionally, the human melanoma cells over-expressing CCR4 were more tumorigenic and caused a higher load of brain metastasis in mouse model." (PMID 36527157, 2022). "The CCR4-mediated Treg cell attraction into melanomas, however, seems to be caused by the alternative CCR4 ligand CCL2." (PMID 31028434, 2019). "All these findings prompted us to investigate if melanoma-associated CCR4 is functionally involved in brain metastasis." (PMID 28415693, 2017). "CCR4 was a member of this signature: Its expression was higher in cells originating in brain-metastasizing melanoma variants than in cells of the corresponding cutaneous variants." (PMID 28415693, 2017). "To this end, we generated a CCR4-overexpressing cutaneous variant of the YDFR melanoma by viral transduction of CCR4 DNA." (PMID 28415693, 2017). "The expression of the chemokine receptor CCR4 was found significantly higher in one melanoma brain metastatic variant compared to the corresponding tumor implanted in the flank." (PMID 23750336, 2013). "We found that CCR4 expression is significantly higher (p < 0.05) on local melanoma variants propagating in 3D culture than on the same cells growing under 2D conditions, suggesting that the extracellular matrix in 3D cultures has a regulatory effect on the expression of CCR4." (PMID 28415693, 2017). "Treg cells can infiltrate tumors such as melanoma by expressing the C-C chemokine receptor type 4 (CCR4), and depleting Tregs can effectively produce anti-tumor immune responses." (PMID 39936954, 2025). "Targeting immunosuppressive cells, such as CCR4+ Tregs in melanoma, shows promise, with CCR4 antibodies depleting Tregs in vivo and in vitro." (PMID 40443678, 2025). "Specifically, the CCR4/CCL17 axis promotes melanoma cells to migrate toward astrocytes and TEM via the BBB." (PMID 37190188, 2023). "Here, CCR2 expressed by melanoma derived from the brain was 7-fold higher compared with melanoma in the skin, whereas a 2-fold increase was observed for CCR4’s expression." (PMID 35980743, 2022). "Elevated levels of CCR4 is another predictive marker for melanoma brain metastasis in an analysis of melanoma brain metastasis cell lines." (PMID 36527157, 2022). "CCR4 is significantly higher in paired clinical specimens of melanoma metastases than in samples of primary tumors from the same patients." (PMID 36527157, 2022). "The chemoattraction of CCR4‐expressing melanoma cells to the corresponding brain‐derived ligands was instrumental in the formation of brain metastasis." (PMID 32761606, 2021). "Cross talk between melanoma cells and microglia, astrocytes and brain endothelial cells (EC) upregulated CCR4 expression on melanoma cells and CCL17/CCL22 expression by and secretion from the brain cells." (PMID 32761606, 2021). "In a murine melanoma tumor model, a treatment with the CCR4 antagonist in both prophylactic and therapeutic settings is more efficient than cyclophosphamide to elicit Ag-specific CD8+ T cells and partly inhibit tumor growth." (PMID 33924428, 2021). "In melanoma patients, the anti-CCR4 antibody, KM2160, effectively depletes effector Tregs and promotes the immune response of CD8+ T cells in vivo." (PMID 34806028, 2021). "CCR4 is a second target with potential dual effects; CCR4 contributes to melanoma metastasis to the brain, and it is also expressed on the most suppressive tumour-infiltrating T-regs." (PMID 34830780, 2021). "CCR4 overexpressing melanoma cells were more highly tumorigenic and generated more brain micrometastases than control cells." (PMID 32761606, 2021). "A study from our laboratory established that the chemokine receptor CCR4 is a member of the molecular signature of melanoma brain metastasis and that its chemokine ligands CCL17 and CCL22 are expressed in microenvironmental brain cells." (PMID 32761606, 2021).
melanoma (continued). "Human TH2-like Tregs (GATA3+CCR4+) have the highest chemotaxis, viability and suppressive function, and are enriched in melanoma and colorectal cancer." (PMID 34177968, 2021). "We have previously shown that CCR4 is highly expressed by tumor-infiltrating Treg cells in melanoma patients." (PMID 34907192, 2021). "CXCR3 expression on antigen-experienced peripheral CD8+ T cells has been associated with prolonged survival in patients with stage III melanoma, and CCR4 was highly co-expressed with CXCR3." (PMID 34454518, 2021). "The expression of CCR4 was significantly higher in paired clinical specimens of melanoma metastases than in samples of primary tumors from the same patients." (PMID 33466236, 2021). "Environmental cues – in particular those provided by brain parenchymal cells such as astrocytes - seem to help specifically guide melanoma cells that express CCR4 or CD271, potential “homing receptors”." (PMID 30053879, 2018). "Forcing the expression of CCR4 in melanoma cells increased their tumorigenicity and the number of brain metastases." (PMID 30053879, 2018). "Employing melanoma variants, we established a molecular signature of melanoma brain metastasis (MBM) including among others, the chemokine receptor CCR4 and the tight junction protein Claudin-1." (PMID 28415693, 2017). "The expression of this chemokine receptor was regulated by the brain microenvironment, as brain derived-soluble factors upregulated CCR4 expression in melanoma cells." (PMID 28415693, 2017). "We show that CCR4 is more highly expressed by brain metastasizing melanoma cells than by local cutaneous cells from the same melanoma." (PMID 28415693, 2017). "Our previous results have indicated that the chemokine receptor CCR4 is significantly upregulated in brain-metastasizing melanoma cells." (PMID 28415693, 2017). "Taken together, these results clearly indicate that CCR4 is functionally involved in the tumorigenicity of melanoma as well as in the formation of brain metastasis." (PMID 28415693, 2017). "Flow cytometry analysis revealed that brain metastasizing human melanoma cell variants (YDFR.CB4, M12.CB3 and M16.CB2 - referred here after as HBMMC), expressed higher levels of CCR4 than cells from the corresponding local YDFR.C, M12.C and M16.C variants." (PMID 28415693, 2017). "Blocking CCR4 with a small molecule CCR4 antagonist in-vivo, reduced the tumorigenicity and micrometastasis formation of melanoma cells." (PMID 28415693, 2017). "Functionally, human melanoma cells over-expressing CCR4 were more tumorigenic and produced a higher load of spontaneous brain micrometastasis than control cells." (PMID 28415693, 2017). "The aim of this study was to determine the functional significance of CCR4 in melanoma brain metastasis." (PMID 28415693, 2017). "Chemo attraction of CCR4-expressing melanoma cells towards CCR4 ligands in the brain seems to be a major mechanism by which this receptor exerts its pro-metastatic activity." (PMID 28415693, 2017). "The results demonstrated that microglia-derived soluble factors upregulated the expression of CCR4 by melanoma cells." (PMID 28415693, 2017). "It should be noted that the forced expression of CCR4 in melanoma cells (yielding CCR4hi cells) enhanced also the spontaneous migration capacity of the melanoma cells." (PMID 28415693, 2017). "We demonstrated above that CCR4 facilitates melanoma cell migration towards astrocyte-derived soluble factors." (PMID 28415693, 2017). "We previously identified the chemokine receptor CCR4 as part of the molecular signature of melanoma brain metastasis." (PMID 28415693, 2017). "To assess the effect of CCR4 on melanoma cell viability we utilized an XTT-based assay to determine the viability of CCR4hi and CON cells in culture." (PMID 28415693, 2017). "Vemurafenib-resistant melanoma cells expressed higher levels of CCR4 than vemurafenib-sensitive cells, which are less malignant." (PMID 28415693, 2017).